SACK1H (scaffolding CK1 anchoring protein H)
Description:
May play a major role in the structural organization and calcification of developing enamel. May play a role in keratin cytoskeleton disassembly by recruiting CSNK1A1 to keratin filaments. Thereby, it may regulate epithelial cell migration.
Synonyms: FAM83H; FLJ46072; AI3; AI3A
Tractability: PROTAC: ubiquitination databases record sites on it; its protein half-life has been measured.
Gene: Protein-coding gene on chromosome 8 (143,723,933 to 143,740,732, reverse strand). Ensembl gene ENSG00000180921.
Subcellular location: Cytoplasm, cytoskeleton; Cytoplasm
Subcellular location (Human Protein Atlas): Cytosol
Gene Ontology:
Molecular function: keratin filament binding; protein binding; protein kinase binding
Biological process: intermediate filament cytoskeleton organization; positive regulation of cell migration; protein localization to cytoskeleton; signal transduction
Cellular component: cytoplasm; keratin filament; cytoskeleton
Genetic constraint (gnomAD): Loss-of-function variants: 24 observed, 30.19 expected, observed/expected ratio (o/e) 0.79, 90% interval 0.57 to 1.12. The synonymous counts are far from expectation, so gnomAD's model fits this gene poorly and the ratio says little. Missense variants: 2,038 observed, 1,626.8 expected, observed/expected ratio (o/e) 1.25, 90% interval 1.21 to 1.3. Synonymous variants: 1,013 observed, 749.8 expected, observed/expected ratio (o/e) 1.35, 90% interval 1.28 to 1.42.
Homologues: Orthologues: chimpanzee FAM83H (99% identical), macaque FAM83H (97% identical), pig FAM83H (87% identical), mouse Fam83h (87% identical), rat Fam83h (86% identical), guinea pig FAM83H (86% identical), dog FAM83H (85% identical), tropical clawed frog fam83h (43% identical), zebrafish fam83hb (31% identical), zebrafish fam83ha (28% identical). Paralogues in human: SACK1B (17% identical), SACK1G (14% identical), SACK1C (14% identical), SACK1D (12% identical), SACK1E (11% identical), SACK1F (11% identical), SACK1A (10% identical).
Diseases named in the same sentence as SACK1H in open-access papers:
SACK1H is named in the same sentence as 52 diseases in open-access papers, as found by Europe PMC text mining. Sharing a sentence is not in itself a finding about the gene and the disease.
SACK1H shares sentences with these, for which no sentence is quoted: cancer (24 papers); tumor (17); colorectal cancer (16); amelogenesis imperfecta (10); gastric cancer (10); osteosarcoma (10); hepatocellular carcinoma (7); colon carcinoma (6); prostate carcinoma (6); uterine cancer (6); breast carcinoma (5); clear cell renal cell carcinoma (5); pancreatic cancer (5); liver cancer (4); cervical cancer (3); head and neck cancer (3); hypocalcified amelogenesis imperfecta (3); kidney cancer (3); lymph node metastasis (3); ameloblastoma (2); astrocytoma (2); brain astrocytoma (2); brain tumors (2); glioma (2); lung carcinoma (2); oligodendroglioma of the brain (2); ovarian carcinoma (2); renal cell carcinoma (2); adenocarcinoma (1); bladder urothelial carcinoma (1).
A further 22 diseases each share a sentence with SACK1H in 1 paper.